CD69 (CD69 molecule)
Diseases named in the same sentence as CD69 in open-access papers (continued):
Sharing a sentence is not in itself a finding about the gene and the disease.
tumor (continued). "Consistent with the earlier findings, Rag2−/−‐OT1‐iHPC‐treated mice had infiltrating effector T cells (CD44high CD62Llow CD69+ CD25+) in the tumour and memory T cells (CD44high CD62Lhigh CD69− CD25−) in the spleen." (PMID 36592612, 2023). "A reduced fraction of CTCL skin NK cells expressed the maturation marker CD57, the cytotoxic protein granzyme B and the activation marker CD69, indicating reduced tumor-killing abilities of the NK cells." (PMID 37691935, 2023). "CpG-Tag-NP immunization led to increased accumulation of CD8+ and CD4+ T cells expressing the activation marker CD69 in BALF when immunized mice were challenged with 4T1 tumor cells via tail vein injection." (PMID 36839766, 2023). "Overall, these data suggest that CD69 immuno-PET is able to detect changes in the tumor immunobiology prior to changes in tumor size, strengthening its potentially useful as a predictive biomarker of ICI responses." (PMID 37426447, 2023). "CD69 expression is known to play an important role in regulating the severity of various murine inflammation models, including tumor immunity." (PMID 37766179, 2023). "Modulation of the innate immune system with monoclonal antibodies to host CD69 provides a novel means to antagonize tumor growth and metastasis." (PMID 37039643, 2023). "Another study reported that the proportion of peripheral NK cells expressing CD69 significantly increased in NSCLC patients with higher tumor stages compared with stage I and the healthy controls." (PMID 37180581, 2023). "Donor‐derived OT1 CD8+ T cells in TdLNs (tumor‐draining lymph nodes) also displayed decreased activation, as evidenced by the reduced expression of CD69 and IFN‐γ in NK‐depleted hosts compared with control hosts." (PMID 36807566, 2023). "Following 48 h treatment with post-FLOT and post-CROSS tumour conditioned media the frequency of CD69+ T cells in culture negatively correlated with the levels of soluble immunosuppressive pro-angiogenic factors in the conditioned media from ex vivo explants." (PMID 35986757, 2023). "We show CD69 expression is upregulated upon T-cell activation and on tumor-infiltrating lymphocytes (TIL) in response to immunotherapy." (PMID 37426447, 2023). "Noteworthy, also T cells expressing CAR under CD69 promoter demonstrated tumor control, albeit less potent than under PD-1." (PMID 37277433, 2023). "ACM derived from OGJ patients with late-stage tumours significantly decreased the expression of CD69 on the surface of CD4+ T cells compared with untreated cells (untrx: 7.43 ± 0.8 vs. late-stage: 4.29 ± 1.1%, p = 0.005)." (PMID 36790524, 2023). "We further observed that sTRM cells were proliferated and secreted large amounts of pro-inflammatory factors into the skin environment to inhibit tumor growth after the FTY720 blockage of infiltrating activated CD69+CD103-TRM cells into skin tissue." (PMID 37407600, 2023). "Increased expression of CD69 was detected in tumor-infiltrating ILCs in treatment-resistant patients." (PMID 37000496, 2023). "The combination of CD4+ T cell depletion and PD-L1 blockade significantly increased the proportion of CD44+CD69+CD8+ T cells in CT26 tumor tissues." (PMID 36969495, 2023). "Here, tumor size correlated better with the percentage of activated or resident T helper cells of all live cells (CD4 + CD69 +)." (PMID 37118819, 2023). "Mechanistically, T-αFGL2 cell treatment increased the number of CD69+CD8+ brain-resident memory T cells in tumor-bearing mice via a CXCL9/10 and CXCR3 chemokine axis." (PMID 36759517, 2023). "NK cell coculture with infected tumor cells for 12 h resulted in slightly increased CD69 expression for MeVac compared to mock infection which was however not observed for MV-NIS." (PMID 36765035, 2023). "The expression of CD25 and CD69 on the surface of B7-H3-CAR-Jurkat cells was higher than that on the surface of Jurkat cells after co-incubation with tumour cells with high expression of B7-H3 antigen." (PMID 36941687, 2023).
tumor (continued). "In vitro experiments with oncolytic reovirus showed that DCs loaded with infected tumor cells secreted NK chemotactic factors and induced CD69 upregulation and IFNγ expression in NK cells, which in turn promoted DC maturation." (PMID 36765035, 2023). "We also found that CD8+ T cells infiltrating tumor tissue express CD69 to some extent and its expression correlate with PD-1." (PMID 37655095, 2023). "Tumor‐reactive CD39 − CD69− TILs were capable of self‐renewal and expansion and demonstrated superior antitumor response and persistence in vivo." (PMID 36028997, 2023). "This is further indicated by the enhanced frequency of PD-1+ effector T cells and CD69+ effector T cells in the tumor upon ICB+DT compared to DT alone." (PMID 37089449, 2023). "We characterized the T cell responses driven by the EGFRvIII-DBTE in an activation assay against U87vIII cells and observed that EGFRvIII-DBTE induced CD69 activation in T cells and anti-tumor cytokine release in both CD8+ and CD4+ T cell populations." (PMID 36915911, 2023). "In vivo mouse tumour models, compared with anti-CLDN18.2, anti-CLDN18.2-anti-CD28 showed a greater increase in the percentage of CD8+ T cells and higher expression of CD69 on CD8+ T cells in tumour tissues as well as a greater reduction in tumour burden." (PMID 36969060, 2023). "A large fraction of tumor-infiltrating MCMV-specific CD8pos T cells expressed CD69, indicating their differentiation into tumor-resident memory T cells." (PMID 37568582, 2023). "CD69 expression on tumor-infiltrating leukocytes was assessed using single-cell RNA sequencing (scRNA-seq) data from patients with recurrent GBM receiving ICI." (PMID 37426447, 2023). "IL-15 is more effective in upregulating the expression of NKp46 and NKp30, which are involved in the recognition and killing of tumor- and virus-infected cells; IL-15 also increases the CD69 expression, which is an early activation marker on T and NK cells." (PMID 38106519, 2023). "CD69 was demonstrated to regulate T-cell migration and retention in tissues, playing an important role in inducing the exhaustion of tumor-infiltrating T cells." (PMID 36417130, 2023). "17.7 (±4.7)% and 17.1 (±6.5)% of the cells showed the expression of CD25 in PBL/PDL1-BiTE/tumor/ASCs or C.M. (P > 0.05), whereas these percentages were 56.9 (±5.4)% and 64.3 (±8.4)% for CD69, respectively (P > 0.05)." (PMID 39282109, 2023). "As an activation marker, CD69 is generally considered as the biomarker of enhanced anti-tumor activities of effector lymphocytes." (PMID 37180581, 2023). "In the NE(PD1nb) group, the tumor‐infiltrating CD4+ T‐cells showed higher expression of CD69 than those in the other groups by at least threefold." (PMID 37565362, 2023). "Compared to NK cell only controls and mock treatment of tumor cells, CD69 expression on NK cells was increased after exposure to MV-infected tumor cells." (PMID 36765035, 2023). "After the co-culture of engineered T cells with tumor cells for 24 h, we measured the expression levels of CD69 and CD25 in T cells." (PMID 37670338, 2023). "Several papers indicated the important role of CD69 in inducing the exhaustion of tumor-infiltrating T cells." (PMID 37655095, 2023). "Of note, CD69 expression in the circulation was negligible compared to the tumor, likely due to the rapid up- and down-regulation of this marker after T cell activation." (PMID 37089449, 2023). "Monomeric BBζ CARs maintained functionality in regard to specific killing and degranulation, as well as CD25, CD69 and 4-1BB upregulation on coincubation with tumor cells." (PMID 37932456, 2023). "Even though Lenti‐HPV‐07 treatment led to complete tumor eradication, there was an increase in the frequency of intra‐tumoral CD44dim CD69− KLRG1+ exhausted T cells, which most likely resulted from continuous checkpoint signaling and antigenic stimulation." (PMID 37675835, 2023).
tumor (continued). "The regulation of critical signaling molecules involved in T-cell activation, such as CD38 and CD69, further underscores melatonin’s role in modulating T-cell behavior and immune responses within the tumor microenvironment." (PMID 38260850, 2023). "Similar proportions of CD56dim/CD16+ NK cells isolated from the tumor microenvironment of NSG‐Tg(Hu‐IL15) mice express functional markers CD69, CD8, and NKG2D, and produce granzyme A and granzyme B when compared to NSG mice." (PMID 35959876, 2022). "About 30% of tumor-infiltrating lymphocytes (TILs) in the tumor microenvironment of gastric adenocarcinoma are CD69+CD103+ tissue-resident memory T cells (TRMs) cells." (PMID 36341377, 2022). "Animals injected with the parasite lysate presented a higher frequency of CD11b+/Ly6G+Ly6C+ cells in the tumours together with an increase in CD69 expression in NK cells, indicating a greater activation rate of these cells." (PMID 36499361, 2022). "The percentage of CD69 on TDLN stem-like T cells was correlated very well with tumor size at early stage." (PMID 36229613, 2022). "Our study found that CD69 presented low expression in tumor tissue and was considered a good prognostic gene." (PMID 36117156, 2022). "Our results showed that combination treatment significantly induced CD69+ CD8+ infiltration with a significant increase in CD69+ CD8+ PD-1− population on both sides of tumor." (PMID 36513720, 2022). "Fourteen TIL populations from 14 tumour specimens were further characterized via flow cytometry for the markers: CD69, HLA-DR, T-bet, CD45RA, Ki67, CD39, PD-1, and FOXP3." (PMID 35158816, 2022). "Correlation analysis revealed that in various TCGA cancer datasets, CD69 expression level correlated positively with most immune checkpoints and tumor-infiltrating immune cells, while SBK1 expression level correlated negatively with infiltrating immune cells." (PMID 36045683, 2022). "We then assessed by flow cytometry activation markers associated with effector function (CD69, CD44 and 2-NDGB) expressed on tumor infiltrating CD4+ and CD8+ T cells from anti-PD-1 and anti-PD-L1 refractory mice." (PMID 35355980, 2022). "Our combination was able to induce CD8+ PD1- with high CD44+ and CD69+ expression on both sides of tumor." (PMID 36513720, 2022). "Based on the expression of activation markers (CD69 and HLA-DR), the expanded TILs likely exhibit an activated state and suggest certain degree of tumour specificity." (PMID 35158816, 2022). "oAd-mCD47nb-Fc significantly upregulated CD69 expression on tumor-infiltrating CD8+ T cells in comparison to counterpart." (PMID 35837100, 2022). "It is shown that CLEC7A, VCAN, and KYNU were significantly upregulated in monocytes, BIRC3 and SOD1 were mainly distributed in T cells, CCL20 was highly expressed in tumor cells, and CD69 was highly expressed in B cells." (PMID 35480896, 2022). "They found that CD69 plays an important role in antitumor immunity, especially in regulating the depletion of tumor-infiltrating T cells and in weakening the antitumor immune response." (PMID 36117156, 2022). "Co-culture of BAFF CAR-T cells with these tumor cells results in induction of activation marker CD69, degranulation marker CD107a, and multiple proinflammatory cytokines." (PMID 35017485, 2022). "For instance, higher expression of CD69 and PIK3R5 was associated with enhanced sensitivity of tumor cells toward multiple chemotherapeutics such as nelarabine, fluphenazine, and dexamethasone decadron." (PMID 36497225, 2022). "Accordingly, we observed a significantly higher abundance of CD69 T cells in the spleen of SUMOi-treated mice, which is in line with our previous data that SUMOi activates tumor-infiltrating CD8+ T cells." (PMID 35499080, 2022).
tumor (continued). "Hsp70-primed, CD3−/CD56+ NK cells expressing an elevated cell surface density of C-type lectin receptors, including CD94 and the activation marker CD69, efficiently recognize and kill membrane Hsp70-positive tumor cells via granzyme B-mediated apoptosis." (PMID 36428793, 2022). "Mice given unmodified Neo-LNP showed a significant increase in CD69+ tumor-infiltrating T cells and the expression levels of CD40 in cDC1 (CD11c+ XCR1+)." (PMID 36311701, 2022). "We also quantified expression of CD63, CD35/CD21, and CD69 on eosinophils during EO771 tumor growth in the lungs since these are established markers of eosinophil activation and/or secretion." (PMID 35756626, 2022). "Within the present study, a significant decrease in CD3+CD4+CD69+ cells was observed at week six, potentially due to the removal of the immunosuppressive tumour." (PMID 35154142, 2022). "Some, like CD69 were upregulated at d2 in the tumor, and a number of genes including CD8a and CD8b1 are downregulated in the tumor at d2; however, these changes were not significant when corrected for multiple comparisons." (PMID 36056093, 2022). "Cd69-deficient mice show a reduced tumour growth and the downregulation of CD69 by monoclonal antibodies enhanced the anti-tumour immunity." (PMID 35930205, 2022). "For example, up-regulated CD69 and PIK3R5 were associated with higher tumor cell sensitivity with various chemotherapeutics like nelarabine, fluphenazine, and dexamethasone decadron." (PMID 36497225, 2022). "ILCs were defined as Lineage(Lin)−CD7+CD127−CD56+CD45RO+, a population that was enriched in CRC tissues and exhibited marked antitumor activity with a tumor-resident profile (CD103+CD69+)." (PMID 36451828, 2022). "Cells in clusters 4 and 5 both expressed CD69, consistent with tissue residence and their predominance in the tumor." (PMID 35584630, 2022). "Meantime, in non-TNBC lymph node metastases, LGALS1 expression induced the apoptosis of activated T cells and promoted the angiogenesis of metastatic tumor tissue by interacting with CD69." (PMID 34611125, 2021). "In particular, CCL19 is a chemotactic factor involved in recruiting CD4+CD25+CD69- T-regs to zones of T cell infiltration in the tumor micro-environment." (PMID 34298673, 2021). "The frequency of activated NK cells (gated as CD69+ NK cells) in the tumor also increased overall, a trend similar to that observed in vitro." (PMID 33558639, 2021). "We found that tumor-infiltrating PD-1+ CD3+ CD+ T cells expressed higher CD69 and HLA-DR than tumor-infiltrating PD-1− CD3+ CD+ T cells isolated from the same samples, which suggest PD-1+ subset in tumor-infiltrating CD3+ CD+ T cells are more activated." (PMID 33934206, 2021). "Upregulation of the activation marker CD69 on T cells isolated from day 10 DM6‐Mut xenografts confirmed that these cells are activated upon entry into the tumor microenvironment." (PMID 33552509, 2021). "For example, activated CDC1 preferentially promote CD69 downregulation on CD8+ TRMs in the tumor, whereas in the colon, the CDC1 mediate this effect on CD8+ former TRMs or non-TRMs." (PMID 34680397, 2021). "Within the tumor-associated CD8 + T cell population, anti-mCTLA-4 treatment resulted in 73% CD69 + positivity which was significantly greater than SPD alone (43%; p < 0.01)." (PMID 34331595, 2021). "Although CD69 is generally associated as the earliest activation cell surface marker on leukocytes, it has been reported that CD25−FoxP3−CD69+ cells from a tumor-bearing mouse can inhibit CD4+ T-cell proliferation in vitro and in vivo." (PMID 34769406, 2021). "The CD8+ CD69+ cell activation has been shown to be a key factor in tumor control, at least in experimental models." (PMID 34442004, 2021). "The enriched GD2-B7H3 T cells upregulated the B7H3 CAR, CD69 activation marker, and intracellular cytokines only in the presence of double-positive target cells and showed improved anti-tumor effect at lower E:T ratios." (PMID 33479234, 2021).
tumor (continued). "CCL20, MMP14, and PCDH7 were upregulated in LUAD tumor tissues and linked to poor clinical outcomes, while BTG2, CD69, GPC3, IL7R, and NMUR1 are the opposite." (PMID 34881236, 2021). "Tumor-induced SPAS-1 specific T cells in NLTs adopted phenotypes consistent with a tissue-resident population including expression of CD69 (right)." (PMID 34162858, 2021). "It is interesting that tumor-infiltrating PD-1+ CD3+ CD+ T cells expressed higher levels of both CD69 and HLA-DR than tumor-infiltrating PD-1+ CD38− CD+ T cells." (PMID 33934206, 2021). "Tumor-infiltrating NK cells in WASpL272P mice had a higher expression of the activating marker CD69, suggesting increased activation of WASpL272P NK cells." (PMID 33621210, 2021). "CD69 was shown in many studies to induce NK cell cytotoxicity against tumor cells and that CD69 blockade reduced NK cell cytotoxic capacity to the same level as not activated NK cells." (PMID 33802954, 2021). "The CD69- cells showed oligoclonal expansions capable of lysing autologous tumor cells, while the CD69+ cells showed an increased inhibitory-immune checkpoint expression." (PMID 33717170, 2021). "Other markers of activation/exhaustion were also elevated on tumor-infiltrating T cells after mRIPO (CD69, CTLA4, PD1, TIM3)." (PMID 33767151, 2021). "This is consistent with reduced DNAM-1 and increased CD69 expression on NK cells exposed in vitro to tumor target cells expressing DNAM-1 ligands." (PMID 33435153, 2021). "The results were further confirmed by the relatively higher amounts of CD69+/CD25‐ TILs on the tumor slices after thiolated nano‐vaccine inoculation; the results were then proved by TUNEL staining of excised tumor slices." (PMID 33747739, 2021). "Specifically, tumor-infiltrating and tumor-associated NK cells from STAT3-deficient tumor-bearing mice express enhanced levels of NKG2D, CD69, FASL, granzyme B, perforin, and IFN-γ, reducing tumor growth and improving survival." (PMID 34025641, 2021). "The flow cytometry analysis showed significant increases in the ratio of M1:M2 tumor-associated macrophages, meanwhile the number of CD4+, CD8+, CD4+CD69+ and CD8+CD69+ lymphocytes were increased after SCH772984 treatment." (PMID 33816301, 2021). "Most of these tumor-infiltrating NK cells were CD69+ and resided within the few outermost cell layers of the TuMT." (PMID 34925361, 2021). "EOC2 only reduced CD69 and IFNγ protein level on T cells in response to TuCM conditioning combined with tumor cell co‐culture." (PMID 33755340, 2021). "High SDI was positively correlated with tumor infiltration of CD4+ CD69+ and CD4+ PD1+ T-cells at week 3, and CD4+ ki67+ T-cells at week 5 (P = 0.004, Q = 0.14; P = 0.036, Q = 0.21; P = 0.004, Q = 0.07, respectively)." (PMID 33619320, 2021). "Many tumor-infiltrating memory T cells expressed the TRM marker CD69, and TRMs were subcategorized as CD103+ or CD103−." (PMID 33479027, 2021). "In this way chemokine receptors that are induced by activation are likely to be enriched on the antigen-specific populations in the tumor environment, akin to the activation markers CD69 and CD39." (PMID 33968757, 2021). "Next, we compared the degree of activation of tumor-infiltrating PD-1+ CD3+ CD+ T cells with tumor-infiltrating PD-1+ CD38− CD+ T cells using CD69 and HLA-DR, which are the markers of T cell activation." (PMID 33934206, 2021). "Tumor and splenic lymphoid DCs, CD69+ NK cells and IFNγ+ CD4+ T cells were significantly increased in CTX-treated tumors compared to controls but there was no further increase in VTX+ CTX-treated tumors compared to CTX alone." (PMID 33452311, 2021). "• Tumors from non-responders to monotherapy often express other immune checkpoints and higher gene expression profile of EOMES+, CD69+, CD45RO+ T cells is associated with greater tumor shrinkage in both therapies." (PMID 32265933, 2020).